PBX1 (PBX homeobox 1)
Description:
Transcription factor which binds the DNA sequence 5'-TGATTGAT-3' as part of a heterodimer with HOX proteins such as HOXA1, HOXA5, HOXB7 and HOXB8. Binds to the DNA sequence 5'-TGATTGAC-3' in complex with a nuclear factor which is not a class I HOX protein. Has also been shown to bind the DNA sequence 5'-ATCAATCAA-3' cooperatively with HOXA5, HOXB7, HOXB8, HOXC8 and HOXD4. Acts as a transcriptional activator of PF4 in complex with MEIS1. Also activates transcription of SOX3 in complex with MEIS1 by binding to the 5'-TGATTGAC-3' consensus sequence (By similarity). In natural killer cells, binds to the NFIL3 promoter and acts as a transcriptional activator of NFIL3, promoting natural killer cell development (By similarity). Plays a role in the cAMP-dependent regulation of CYP17A1 gene expression via its cAMP-regulatory sequence (CRS1) (By similarity). Probably in complex with MEIS2, involved in transcriptional regulation by KLF4. Acts as a transcriptional activator of NKX2-5 and a transcriptional repressor of CDKN2B (By similarity). Together with NKX2-5, required for spleen development through a mechanism that involves CDKN2B repression (By similarity). [Isoform PBX1b]: As part of a PDX1:PBX1b:MEIS2B complex in pancreatic acinar cells, is involved in the transcriptional activation of the ELA1 enhancer; the complex binds to the enhancer B element and cooperates with the transcription factor 1 complex (PTF1) bound to the enhancer A element.
Synonyms: CAKUHED
Tractability: PROTAC: ubiquitination databases record sites on it; its protein half-life has been measured.
Gene: Protein-coding gene on chromosome 1 (164,555,584 to 164,899,296, forward strand). Ensembl gene ENSG00000185630.
Subcellular location: Nucleus
Subcellular location (Human Protein Atlas): Nucleoplasm; Cytosol; Nuclear bodies
Pathways (Reactome):
Developmental Biology: Activation of anterior HOX genes in hindbrain development during early embryogenesis; Transcriptional regulation of pluripotent stem cells
Signal Transduction: NOTCH3 Intracellular Domain Regulates Transcription
Gene Ontology:
Molecular function: DNA binding; protein binding; RNA polymerase II transcription regulatory region sequence-specific DNA binding; sequence-specific double-stranded DNA binding; transcription cis-regulatory region binding; transcription coregulator binding; transcription corepressor binding; DNA-binding transcription activator activity, RNA polymerase II-specific; DNA-binding transcription factor activity; DNA-binding transcription factor activity, RNA polymerase II-specific; RNA polymerase II cis-regulatory region sequence-specific DNA binding; DNA-binding transcription factor binding; sequence-specific DNA binding
Biological process: animal organ morphogenesis; brain development; embryonic organ development; eye development; natural killer cell differentiation; neuron development; positive regulation of transcription by RNA polymerase II; regulation of DNA-templated transcription
Cellular component: cytoplasm; nuclear body; nucleoplasm; nucleus; RNA polymerase II transcription regulator complex; chromatin; transcription regulator complex
Genetic constraint (gnomAD): Loss-of-function variants: 4 observed, 43.11 expected, observed/expected ratio (o/e) 0.0928, 90% interval 0.045 to 0.21. The upper end of that interval is the gene's LOEUF score, 0.21, which puts it in group 1 of 6, group 1 being the genes least tolerant of losing a copy. Missense variants: 228 observed, 488.5 expected, observed/expected ratio (o/e) 0.47, 90% interval 0.42 to 0.52. Synonymous variants: 189 observed, 194.45 expected, observed/expected ratio (o/e) 0.97, 90% interval 0.86 to 1.1.
Gene-disease validity (ClinGen):
ClinGen rates the evidence that PBX1 causes each of these diseases.
congenital anomalies of kidney and urinary tract syndrome with or without hearing loss, abnormal ears, or developmental delay (autosomal dominant): Definitive.
Cancer hallmarks: escaping programmed cell death (promotes); angiogenesis (promotes); change of cellular energetics (promotes)
Homologues: Orthologues: chimpanzee PBX1 (100% identical), guinea pig PBX1 (100% identical), macaque PBX1 (100% identical), mouse Pbx1 (100% identical), rabbit PBX1 (100% identical), rat Pbx1 (100% identical), dog PBX1 (99% identical), Drosophila melanogaster exd (63% identical), pig PBX1 (54% identical), Caenorhabditis elegans ceh-20 (46% identical), Drosophila melanogaster hth (19% identical), Caenorhabditis elegans ceh-60 (19% identical), and 3 more. Paralogues in human: PBX3 (85% identical), PBX2 (76% identical), PBX4 (60% identical), MEIS2 (24% identical), MEIS1 (22% identical), MEIS3 (20% identical), PKNOX2 (19% identical), MEIS3P2 (19% identical), PKNOX1 (16% identical), TGIF1 (12% identical), TGIF2 (8% identical), TGIF2LX (8% identical), and 1 more.
Diseases named in the same sentence as PBX1 in open-access papers:
PBX1 is named in the same sentence as 160 diseases in open-access papers, as found by Europe PMC text mining. Sharing a sentence is not in itself a finding about the gene and the disease. The quoted sentences say what the papers report.
leukemia (79 papers, 2006 to 2026). A malignant (clonal) hematologic disorder, involving hematopoietic stem cells and characterized by the presence of primitive or atypical myeloid or lymphoid cells in the bone marrow and the blood. "Overall, the expression of Meis1–3, Pbx1–3, and their associated partner, Hoxa9, were observed as upregulated in thymoma, pancreatic adenocarcinoma, glioblastoma, glioma, lymphoma, and leukemia when compared to corresponding healthy adult tissues." (PMID 33402862, 2020). "While PBX1 has been extensively studied in leukemia, little is known about the contributions of PBXIP1 and PBX4 in this context." (PMID 41554854, 2026). "PBX1 is negatively regulated in two sets of lung cancer and two sets of leukemia, and positively regulated in a set of breast cancer." (PMID 36101460, 2022). "PBX1 belongs to a family of pre-B cell leukemia transcription factors and is suggested to act as a pioneer factor in breast cancer, remodeling the chromatin to favor the recruitment of estrogen receptor alpha." (PMID 34943938, 2021). "The expression of PBX1 is decreased by camptothecin, which is a topoisomerase poison used to treat leukemia." (PMID 33920951, 2021). "Unexpectedly, in experimental models designed to study the mechanism by which E2a-Pbx1 induces leukemia, retroviral mediated expression of E2a-Pbx1 in hematopoietic progenitors gives rise to myeloid, not lymphoid leukemia." (PMID 34736527, 2021). "Its expression is upregulated in mixed lineage leukemia (MLL)-rearranged ALL and downregulated in transcription factor E2-alpha (E2A)/pre-B-cell leukemia transcription factor 1 (PBX1)-positive leukemias." (PMID 32408494, 2020). "Meis1–3, Pbx1–3, and Hoxa9 are upregulated in thymoma, pancreatic adenocarcinoma, glioma, glioblastoma, and leukemia/lymphoma when compared to healthy tissue." (PMID 33402862, 2020). "Leukemia derived from this developmental stage usually displays TCF3/PBX1 chromosomal rearrangement, which is commonly found in leukemia derived from pre-B lymphocytes (in more than 90% of cases)." (PMID 32102485, 2020). "Pre-B-cell leukemia homeobox 1 (PBX1) was originally identified as a proto-oncogene in human leukemia." (PMID 28514754, 2017). "One study demonstrated that upregulation of the gene PBX1 in leukemia cells in the CNS microenvironment conferred enhanced leukemia chemoresistance and self-renewal properties." (PMID 28491865, 2017). "Meis1 is often co-ordinately over-expressed in various leukemias with its transcriptional partners the TALE domain protein Pbx1 and one or more homeodomain containing Hox family members, and collaborates with them in accelerating leukemogenesis." (PMID 23308270, 2013). "Considering that PBX1 plays a fundamental role in the development of diverse organs and contributes to various types of cancers, namely leukemia, prostate, ovarian and esophageal cancers, its pioneering functions are likely to apply beyond breast cancer." (PMID 22125492, 2011). "Regarding PBX1, we also noticed the low-molecular-weight band existing in controls and in all leukemia derived cell lines." (PMID 22185299, 2011). "We found that PBX1 acts as a transcription factor to upregulate RNF6 in leukemia cells." (PMID 37324936, 2023). "Chemoresistance may be partially promoted by the transcription factor PBX1, which was found upregulated in leukemia cells in the CNS compared to bone marrow ALL cells." (PMID 31970588, 2020). "The message levels of Meis1 transcriptional partners, and other related proteins, that are often co-ordinately upregulated with it in different leukemias, such as Pbx1 and a number of Hox family members was also found to be elevated in the mutants although to different extents." (PMID 23308270, 2013). "Hence, in E2A-PBX1 positive leukemia, PBX1-dependent survival signaling may be particularly enhanced and promote CNS tropism." (PMID 31970588, 2020). "The four most common leukemia genes in B-ALL children were ETV6/RUNX1, E2A/PBX1, MLL, and BCR/ABL in sequence." (PMID 41195225, 2025).
leukemia (continued). "Other studies showed that PBX1, HOXA, and MEIS1 bind to the MYB gene, activating and dysregulating it in leukemia." (PMID 35743243, 2022). "In leukemia cells, RNF6 is upregulated by the Pre-B-Cell Leukemia Transcription Factor 1 (PBX1) and promotes leukemia progression." (PMID 35926709, 2022). "Wnt/β-catenin pathway dysregulation has been reported in different B-ALL subtypes, such as TFC3/PBX1 B-ALL, where Wnt16b is aberrantly activated by the expression of the E2A-Pbx1 fusion protein to induce leukemia." (PMID 33255367, 2020). "A previous study by Fernando and colleagues also evaluated lncRNA expression signatures in genetic subtypes of human BCP-ALL using 14 ETV6/RUNX1, 15 TCF3/PBX1 and 15 MLL-rearranged leukemia specimens." (PMID 27650541, 2016). "Using this array, proof of principle was demonstrated by detection of known fusion genes (such as TCF3:PBX1, ETV6:RUNX1, and TMPRSS2:ERG) from all six positive controls consisting of leukemia cell lines and prostate cancer biopsies." (PMID 19152679, 2009). "This included two leukemia cell lines, RCH-ACV and REH, known to carry the TCF3:PBX1 and ETV6:RUNX1 fusion genes, respectively, and four prostate cancer samples positive for the TMPRSS2:ERG fusion gene." (PMID 19152679, 2009). "Together, these results suggest that while Pbx1 functions as an early target of MNX1 in preleukemic cells, Pbxip1 and Pbx4 act as secondary (indirect) targets whose altered expression arises with MNX1 leukemia progression." (PMID 41554854, 2026). "However, ETV6::RUNX1, TCF3::PBX1, and T‐ALL had low MTXPG intracellular accumulation in leukemia cells." (PMID 39485718, 2024). "PBX3 (not PBX1 or PBX2) is apparently the most important form of PBX that interacts with MEIS1 in human MLL-r leukemias." (PMID 34698191, 2021).
acute lymphoblastic leukemia (58 papers, 2005 to 2025). Leukemia with an acute onset, characterized by the presence of lymphoblasts in the bone marrow and the peripheral blood. "The oncogene function of the PBX1 protein was first reported in acute lymphoblastic leukemia, where t (1:19), a translocation mutation event, resulted in the fusion of the E2A and PBX1 genes and enhanced PBX1 expression." (PMID 36739270, 2023). "Furthermore, a variant generated by fusion of E2A and PBX1, E2A-PBX1, has been found in 25% of patients with childhood acute lymphoblastic leukemia." (PMID 39129784, 2024). "Preclinical evidence indicates that E2A::PBX1 contributes to the proliferation of T-acute lymphoblastic leukemia (T-ALL) in murine models." (PMID 41226583, 2025). "The variant of PBX1, E2A-PBX1, which is generated by the fusion of E2A and PBX1 in the process of chromosomal translocation, is associated with pre-B-cell acute lymphoblastic leukemia (ALL)." (PMID 39129784, 2024). "In a large set of cancer types (lymphoblastic leukemia, lung adenocarcinomas and squamous cancers, hepatocellular, and bladder cancers, etc.), PBX1 amplification promotes cell proliferation and metastasis." (PMID 36833200, 2023). "However, in B-cell progenitor acute lymphoid leukemia (BCP-ALL) PBX1 is part of the fusion gene TCF3::PBX1, and in Hodgkin lymphoma PBX1 is aberrantly activated, demonstrating that deregulated PBX1 acts as an oncogene in B-cell malignancies." (PMID 39689089, 2024). "In addition to its well-known functions in lymphoblastic leukaemia and a number of cancers, PBX1 was also found to promote hESC self-renewal by corporately binding to the regulatory elements of NANOG with KLF4." (PMID 30217220, 2018). "Another study focuses on the dysregulation of MT1 metallothionein subtypes in TCF3::PBX1 pre-B-cell acute lymphoblastic leukemia (ALL)." (PMID 40806565, 2025). "TBC1D8 was found among differentially expressed genes in pre‐B acute lymphocytic leukemia samples with ALL1/AF4, E2A/PBX1, and BCR/ABL molecular rearrangements, and positively controls cell proliferation." (PMID 31254352, 2019). "A clinical follow-up was conducted on 137 B-ALL children with positive genes (59 cases of ETV6/RUNX1 positivity, 22 cases of E2A/PBX1 positivity, 25 cases of MLL positivity, and 19 cases of BCR/ABL positivity) among 302 children with acute lymphoblastic leukemia." (PMID 41195225, 2025). "For instance, HtrA3 is downregulated in B-cell and T-cell acute lymphoblastic leukemia and acute myeloid leukemia, yet HtrA3 is significantly increased in acute lymphoblastic leukemia where chromosome translocation has occurred at 11q23/MLL or TCF3/PBX1." (PMID 34639128, 2021).
breast carcinoma (29 papers, 2011 to 2025). "In some instances, increased expression of PBX1 is linked to proliferation promotion, as in breast cancer." (PMID 38404687, 2024). "Though changing the regulatory miR-522-3p affinity to PBX1 3'-UTR, the rs6426881 T allele at PBX1 3′-UT is prominently correlated with breast carcinoma and gastric carcinoma." (PMID 38240925, 2024). "PBX1 is a transcription factor whose overexpression is associated with poor prognosis in luminal breast cancers and promotion of metastasis." (PMID 34445129, 2021). "Overall this data strongly suggest that PBX1 protein levels in primary breast cancer are significantly associated with breast cancer progression." (PMID 26215677, 2015). "Our data identifies PBX1 amplification as a functional hallmark of aggressive ERα-positive breast cancers." (PMID 26215677, 2015). "Our analysis using PBX1 transcriptional and protein levels strongly supports the role of PBX1 as a functional biomarker associated with ERα breast cancer progression." (PMID 26215677, 2015). "To elucidate further the potential role of PBX1 as a breast cancer biomarker, we tested the association between its expression and metastatic progression in an additional six independent studies (Affymetrix arrays)." (PMID 26215677, 2015). "Mechanistically, PBX1 amplification impinges on several critical pathways associated with aggressive ERα-positive breast cancer." (PMID 26215677, 2015). "In agreement with cell line data, we found that PBX1 protein levels significantly correlate with ERα, FOXA1 and GATA3 (another important ERα pioneer factor) thus demonstrating that PBX1 is strongly associated with ERα-positive, luminal breast cancer subtypes." (PMID 26215677, 2015). "PBX1 dependent genes were enriched for several important ontological terms associated with breast cancer and endocrine therapy resistance, including Notch signaling, pro-invasive signaling and epithelial and mammary carcinoma." (PMID 26215677, 2015). "Even more, PBX1 expression alone is sufficient to identify a priori ERα-positive breast cancer patients at risk of developing metastasis." (PMID 22125492, 2011). "More importantly, the PBX1-dependent transcriptional program is associated with poor-outcome in breast cancer patients." (PMID 22125492, 2011). "Indeed, they showed high expression of PBX1 is associated with poor survival in ER+ breast cancer patients." (PMID 39358487, 2024). "In addition, FOXA1 and GATA3 are frequently targeted by mutations in breast cancer, while PBX1 is rarely affected by somatic mutations (V117M and H425N, 2 out of 892 patients)." (PMID 26215677, 2015). "Taken together, this suggests that PBX1 drives a very specific transcriptional response underlying progression in ERα-positive breast cancer and reveal the potential prognostic potential for PBX1 within this breast cancer subtype to predict outcome." (PMID 22125492, 2011). "Finally, we present evidences suggesting that PBX1 may be amplified in over 10% of ERα-positive breast cancer patients and amplification is associated with shorter survival." (PMID 26215677, 2015). "We also investigated the frequency of motifs for other pioneer factors previously reported to play a substantial role in breast cancer, such as AP2γ and PBX1." (PMID 41224124, 2025). "Given the established role of Pbx1 as a pioneer factor for ESR1 in breast cancer cells and its necessity for E2 signaling, we conducted siRNA knockdown of Pbx1 to assess its involvement in E2-induced hernia pathogenesis." (PMID 39903526, 2025). "PBX1 is required in EGF signaling in the ER+ breast cancer cells, as silencing of PBX1 in MCF-7 cells slowed the EGF induced cell proliferation." (PMID 39358487, 2024). "This relationship is an important part of the cell cycle; further studies demonstrated that PBX1 overexpression fosters the proliferation of breast cancer cells and halts the apoptotic process." (PMID 34445129, 2021).